IL4I1 (interleukin 4 induced 1)
Diseases named in the same sentence as IL4I1 in open-access papers (continued):
Sharing a sentence is not in itself a finding about the gene and the disease.
tumor (continued). "It remains unclear how IL4I1 expression is regulated in tumor cells." (PMID 37394584, 2023). "Finally, it is crucial to unravel whether IL4I1 derived from MHCII+ CD163− TAMs initiates the tumor control or is merely a consequence of the tumor regression to develop an accurate therapy targeting this enzyme." (PMID 37526660, 2023). "We also found that ANK1 (P = 0.0018), IL4I1 (P = 1.2e−12), IDO1 (P = 0), IFNG (P = 0)and MAPK12 (P = 2.2e−12) are positively correlated with PD-L1 expression in CRC cancer which has been reported to be associated with worse prognosis and counteract effect of tumor-infiltrating lymphocytes." (PMID 35962343, 2022). "Subclonal ANK1 mutation is related to adverse outcomes of CRC through increasing IL4I1, IDO1, IFNG and MAPK12, which may cause tumor immune escape through the accumulation of immunosuppressive cells such as regulatory T cells and myeloid derived suppressive cells." (PMID 35962343, 2022). "The poor outcome of the subclonal ANK1 mutation may be caused by upregulation of IL4I1, IDO1, IFNG and MAPK12 which showed potential roles in tumor immune evasion through accumulation of immunosuppressive cells such as regulatory T cells and myeloid derived suppressor cells." (PMID 35962343, 2022). "However, patients who express high levels of IL4I1 in their tumor might benefit from a systemic effect of IL4I1 competing with spike, when contracting SARS-COV-2 infection." (PMID 36131918, 2022). "Besides, there may be other Trp metabolizing enzymes involved in tumor immune escape, such as interleukin-4-induced-1 (IL4i1), but at this point, the biology and expression of IL4i1 are still poorly understood." (PMID 35003126, 2021). "Thus, IL4I1 might promote tumor progression through influencing tumor cell motility and adaptive immunity, and regulating the priming of tumor-specific immune cell, such as T cells, B cell and macrophage." (PMID 34717685, 2021). "Thus, the pro-tumor effects of IL4i1 are likely mediated by local anti-ferroptotic pathways via aromatic amino acid metabolism, arguing that an IL4i1 inhibitor may modulate tumor cell death pathways." (PMID 33646117, 2021). "Thus, antitumor CD8+ T cells primed in IL4I1-/- hosts show better control of tumor cells." (PMID 33343572, 2020). "In in vivo xenograft models, subcutaneous implantation of IL4I1-KO HEC-1B and KLE cells into nude mice resulted in significantly reduced tumor growth compared to parental cells." (PMID 41008831, 2025). "Signature gene analysis of IFN‐Mac_CXCL9 revealed 108 significantly up‐regulated genes in tumour‐infiltrating cells including HLA‐A, HLA‐DRB1 and interferon‐regulated genes (CXCL9, CXCL10 and IL4I1)." (PMID 41275425, 2025). "qPCR analysis revealed that CSAD, IL4I1, and P4HA3 were significantly upregulated in tumor specimens, whereas PSAT1 expression was notably reduced in ccRCC tissues (p<0.05)." (PMID 41584585, 2025). "Additionally, IL4I1 may promote tumor growth and metastasis by modulating immune cell functions." (PMID 41008831, 2025). "Inhibition of tumor- or immunosuppressive cell-expressed GLS1, ARG1, iNOS, IDO1, TDO and/or IL4I1 therefore constitutes a promising approach to alleviate tumor-induced immune suppression, either as monotherapy or in combination with other treatment modalities." (PMID 39211039, 2024). "After revealing that IL4I1 is closely related to the immunomodulatory pathway by GSEA analysis, we focused on the invasion of immune cells in the tumor microenvironment." (PMID 38691253, 2024). "Expression of IL4I1 correlates negatively with survival of patients with HCC and IL4I1 expression is higher human HCC tumor samples in comparison with normal samples deposited in the TCGA." (PMID 38769298, 2024).
tumor (continued). "The final amino acid-metabolizing enzyme with a proposed role in tumor immune escape is IL4I1, which is a secreted l-amino acid oxidase (LAAO) first characterized by its interleukin 4-inducible expression in murine and human B cells." (PMID 39211039, 2024). "On the other hand, pRCC showed upregulation of TFPI2, FSTL1, FAS, and PIGR in the epithelial/tumor, C1QTNF3 and GRN in the endothelial, and ITGAX, HLA-DQA1, IL4I1, and CTSC in the immune compartments." (PMID 38703764, 2024). "The results suggest that IL4I1 is a tumor-produced metabolic enzyme that mainly catabolizes tryptophan to activate AHR, enhancing tumor aggressiveness and inhibiting anti-tumor immunity." (PMID 38755125, 2024). "The relationship between IL4I1 and immune infiltration was performed using “Gene Set Variation Analysis (GSVA)” package in TCGA and tumor-immune system interaction database (TISIDB)." (PMID 37434155, 2023). "Recently, Sadik and co-workers proposed that IL4I1 expression may also underlie the resistance of patients against IDO1 inhibition, with activation of the AhR presented as their common mechanism of immune response blockade and promotion of tumor cell malignancy." (PMID 36765849, 2023). "The presence of different IL4i1+ and IDO1+ myeloid cells in tumor-draining lymph nodes is less understood but given that many DCs are migratory, this is an important point to consider." (PMID 37196768, 2023). "Interleukin 4 induced 1 (IL4I1) is reported to have immunoinhibitory and tumor‐promoting effects in several cancers." (PMID 37655051, 2023). "IL4I1 promoted aryl hydrocarbon receptor (AHR)-driven malignant properties and suppressed anti-tumor immunity, even in the presence of immune checkpoint blockade (ICB) and IDO inhibition." (PMID 37507432, 2023). "Related to the proliferation and function of immune cells or tumor progression, T cell proliferation-related genes (TRGs) involve hundreds of protein-coding genes which include CTLA4, HHLA2, PRKCQ, IL4I1, IL20RB, HOMER1, DHPS, and so on." (PMID 36118894, 2022). "Next, we compared the expressions of four important immune checkpoints (PD-L1, CTLA4, IL4I1, and IDO1) between normal and tumor tissues, and between the two clusters." (PMID 35778697, 2022). "Meanwhile, RT-qPCR assays revealed that ALDH6A1, FBP1, HAO2 and PSAT1 were markedly under-expressed in tumor tissues in exceeding 60% cases, and that TYMP, HK3, P4HA3, IL4I1, CYP26A1 and CPT1B were over-expressed in tumor tissues in exceeding 70% cases." (PMID 32737333, 2020). "Isolated PMN-MDSCs from WT mice bearing B16 tumor had much lower level of IL4i1 than Mo-MDSC and F4/80+ macrophages, implying a potential role of IL4i1 in regulating the differentiation of MDSC subpopulations." (PMID 31379854, 2019). "While its roles in tumor immunity and metabolic reprogramming are increasingly recognized, it is important to note that IL4I1 also engages in a variety of non-oncogenic cellular functions." (PMID 41008831, 2025). "IL4I1 and TREM2 macrophage signatures were found in macrophages of the tumor microenvironment." (PMID 41342736, 2025).
tumor (continued). "Moreover, other factors in the tumor microenvironment (TME), such as collagen, induce the expression of interleukin-4 induced 1 (IL4I1), contributing to T-cell exhaustion, and promoting immune evasion." (PMID 40918454, 2025). "Normal tissues of skeletal muscle, colon, and breast had negative or weak staining of IL4I1, and tumor tissues also had weak staining." (PMID 38250074, 2023). "The elevated metabolite levels in ascites may arise from the proximity of this fluid to the tumor as well as the presence of tumor and immune cells, likely expressing IDO1 and/or IL4I1, in the ascites itself." (PMID 36765849, 2023). "Recently, overexpression of IL4I1 was shown to activate AHR and promote tumour progression." (PMID 38062922, 2023). "Our present data shows that IL4I1 produced by MHCII+ CD163− TAMs does not prevent tumor control in our model." (PMID 37526660, 2023). "On the contrary, IL4I1 was found suppressing the effective anti-tumor T-cell response in non-hematological tumors infiltrated by macrophages." (PMID 37434155, 2023). "The outcomes showed that IL4I1 had the strongest positive correlation with the stromal score and the strongest negative correlation with the tumor purity." (PMID 36925967, 2023). "Of note, these cells expressed high levels of IL4I1, an enzyme which accelerates the expansion of CD8+ T cells, and as such this subset may help to support tumor-specific surveillance." (PMID 36253784, 2022). "IL4I1, a metabolic immune checkpoint that activates the aryl hydrocarbon receptor (AHR) through the generation of indole metabolites and kynurenic acid, has been shown to promote cancer cell mobility and metastasis and to suppress anti-tumor immunity." (PMID 36216799, 2022). "Then, transcriptome analysis of sorted Teff from tumor-bearing WT and IL4i1−/− mice verified that IL4I1 deletion increased expression of Teff genes and reduced Ahr levels, suggesting that lack of IL4I1 enhances CD8+ T-cell function." (PMID 33692337, 2021). "IL4I1, ITGB7, and FUT7, which were identified by comprehensive bioinformatic analysis, may play a vital role in the tumour immune microenvironment and hold the potential of enhancing ICB treatment by remodelling glucose metabolism." (PMID 34134578, 2021). "IL4i1, a homolog of LAO1, is expressed by immune cells, including macrophages, T cells, and B cells, upon stimulation by IL4, and has been shown to exert immunomodulatory functions in various tumours and in response to bacterial infections." (PMID 30038322, 2018). "Together, our findings demonstrate that IL4I1+ TAMs and TDO2+ myCAFs synergistically establish an immunosuppressive, ferroptosis-resistant niche via AhR signaling in solid predominant LUAD and offer promising therapeutic strategies to reprogram the tumor microenvironment." (PMID 41431173, 2025). "Strikingly, IL4I1‐K351A‐expressing EG7 cells could not boost OT‐I or B3Z T cell activation in tumor‐T co‐culture setting." (PMID 40583248, 2025). "Besides immunoregulatory effects interfering with tumor immune surveillance, IDO1 and IL4i1 may have a direct influence on controlling cancer cell biology by modulating the composition of the metabolic environment." (PMID 37196768, 2023). "The relevance of our discussion here is that within the milieu where tumor cells themselves acquire IDO1 expression, myeloid IDO1+ cells may also be present in large numbers, and we now know that IL4i1 can also contribute to tryptophan metabolic flux in the same environment." (PMID 37196768, 2023).
tumor (continued). "More importantly, Interleukin-4-induced-1 (IL4I1) as a metabolic immune checkpoint, activates the Aryl hydrocarbon receptor (AHR), circumvents Immune Checkpoint Blockade (ICB) and further elicits major effects in immunosuppression shaping tumor microenvironment." (PMID 37221577, 2023). "Similarly, tumour rupture was observed to be related to negative IL4I1 expression (54.5% vs. 32.4%, p < 0.05)." (PMID 38062922, 2023). "Interestingly, all the genes of the pathway were significantly downregulated in the tumor samples, except for the Branched-Chain Amino Acid Transaminase 1 (BCAT1) and the lysosomal amino acids oxidase Interleukin 4 Induced 1 (IL4I1), which were strongly upregulated." (PMID 36539415, 2022). "We performed liquid chromatography‐tandem mass spectrometry (LC‐MS/MS) to detect Trp metabolism in tumor cells, and found I3A treatment induced Trp and Phe accumulation besides I3A in tumor cells, potentially as a result of a negative feedback loop on Trp metabolism mediated by IL4I1." (PMID 40583248, 2025). "Moreover, IL4I1 induces expression of the inhibitory checkpoint proteins PD-1 and TIM3 on CD8+ T cells upon co-culture with patient-derived tumor organoids, suggesting that IL4I1 inhibitors may need to be combined with immune checkpoint blockade for effective cancer treatment." (PMID 39211039, 2024). "However, despite that IL4I1‐overexpression had not resulted in upregulation of ferroptosis‐related genes in the ML385‐treated group, the tumour volume was significantly increased." (PMID 40071723, 2025). "Moreover, IHC staining validated that the high expression of IL4I1 and CD206 in tumor samples were simultaneously higher than that in adjacent normal tissues." (PMID 37221577, 2023). "On the other hand, the absence of IL4I1 facilitates TMPE development, with consequences for the quality of long-term memory, potentially involved in the better resistance of IL4I1-/- mice to tumor development." (PMID 33343572, 2020).
cancer (63 papers, 2005 to 2025). A tumor composed of atypical neoplastic, often pleomorphic cells that invade other tissues. "Altogether, this information supports that IL‐4 upregulation and consequently IL4I1 secretion represent a real hallmark of mregDCs, explaining their detrimental role in cancer progression and resistance." (PMID 38117000, 2023). "Recently, increased interleukin‐4‐induced‐1 (IL4I1) expression has been reported to catabolize Trp into Kyn and has been implicated in immune regulatory functions in cancer and metastasis." (PMID 37148546, 2023). "Survival outcomes from univariate Cox regression analysis indicated a remarkable association between IL4I1 expression and a dismal prognosis across various cancer types, including GBM, LGG, KIRC, KIRP, LAML, THYM, LIHC, and UVM." (PMID 38250074, 2023). "While no direct evidence for this link exists, yet the association between IL4i1 and cancer is substantial." (PMID 33646117, 2021). "Another immune-associated enzyme that metabolizes amino acids and linked to immune suppression in cancer is interleukin-4-induced-1 (IL4i1), which was discovered in a screen for IL4-regulated cDNAs in B cells." (PMID 33646117, 2021). "Elevated expression levels of IL4I1 have also been reported in primary mediastinal large B-cell lymphoma, thus associating this gene with cancer as well." (PMID 16029492, 2005). "However, little is known about the IL4I1 biology, including the enzymology, the substrate ranges, the role of downstream metabolites, and the association between IL4I1 and different cancers." (PMID 37434155, 2023). "In addition, we recently identified the L-amino acid oxidase interleukin-4-induced-1 (IL4I1) as a novel and very potent upstream regulator of AHR, and we showed that IL4I1 associates more frequently with AHR activity than IDO1 or TDO2 in cancer." (PMID 33920868, 2021). "A pan-cancer analysis through TCGA revealed that IL4I1 is involved in multiple cellular functions and signaling pathways." (PMID 41008831, 2025). "The expression levels of IL4I1 in cancer and adjacent normal tissues were analyzed using the Pan-cancer dataset from the TCGA database." (PMID 41008831, 2025). "First, Pan-cancer transcriptomic analysis of The Cancer Genome Atlas revealed a positive correlation between IL4I1 and GPX4, a key ferroptosis suppressor." (PMID 41354345, 2025). "We conducted a comprehensive evaluation of IL4I1, revealing its potential role as a promoter of cancer and prognostic indicator in patients." (PMID 38691253, 2024). "The IL4I1 enzyme performs a critical role in regulating immune responses throughdiverse mechanisms and has been studied extensively in cancers and inflammatorydiseases." (PMID 39355609, 2024). "In this study, we investigated the expression of IL4I1 and its relationship with the prognosis of patients with cancer." (PMID 38691253, 2024). "Overall, these results corroborate the findings of enhanced MDSC and regulatory T-cell infiltration and reduced CD8+ T-cell infiltration in cancer patients with high IL4I1 expression." (PMID 39211039, 2024). "In contrast, in patients with SKCM, the overexpression of IL4I1 indicates better OS for patients with cancer." (PMID 38691253, 2024). "Thereafter, we evaluated the correlation between IL4I1 methylation and expression in 32 cancer types." (PMID 38691253, 2024). "Elevated expression of IL4I1 has been detected in various human cancer types, including both solid tumors and lymphomas." (PMID 39211039, 2024). "Taken together, although the field studying the role of IL4I1 in cancer immune escape is still in its relative infancy compared to that of IDO1, the pharmacological targeting of IL4I1 offers new prospects for the treatment of cancer patients." (PMID 39211039, 2024). "Similar as observed for IDO1, α-PD-1 treatment can also induce IL4I1 upregulation in cancer patients, and IL4I1 is suggested to potentially constitute a resistance mechanism to immune checkpoint blockade." (PMID 39211039, 2024).